MEIS1 (Meis homeobox 1)
Diseases named in the same sentence as MEIS1 in open-access papers (continued):
Sharing a sentence is not in itself a finding about the gene and the disease.
acute myeloid leukemia (continued). "Moreover, Meis1 as well as Hoxa9 have been shown to be the most critical downstream targets of Mixed Lineage Leukemia (MLL) fusion proteins, and their co-expression is sufficient to induce acute myeloid leukemia, recapitulating MLL-ENL-induced immortalization of myeloid progenitor cells." (PMID 24498346, 2014). "In acute myeloid leukemia (AML) patients, the Methyltransferase 1/WD repeat domain 4 (METTL1/WDR4) complex catalyzes m7G modification of tRNA, enhancing translation efficiency of specific mRNAs (e.g., HOXA9, MEIS1) to maintain AML cell proliferation and stemness." (PMID 41550494, 2026). "In addition, MEIS1 was identified to reduce major histocompatibility complex class II (MHCII)expression in acute myeloid leukemia (AML) cells), MEIS1 overexpression improved survival in patients with AML." (PMID 36836180, 2023).
acute leukemia (17 papers, 2009 to 2025). A clonal (malignant) hematopoietic disorder with an acute onset, affecting the bone marrow and the peripheral blood. "There is a historical association between Meis1 and acute leukemia, a challenging hematological disease characterized by resistance to therapy and frequent relapses." (PMID 39758840, 2024). "Trials have shown promising clinical activity of the selective SYK inhibitor entospletinib in patients with high expressing HOXA9/MEIS1 acute leukemias." (PMID 40188268, 2025). "In module 3, the results indicated that RUNX1, ZBTB16, GATA2 and MEIS1 which involved in the myeloid cell differentiation and the pathogenesis of acute leukemia showed higher levels of expression in cells from the MDS across differentiation." (PMID 38632656, 2024). "MEIS1 overexpression was inversely correlated with relapse and overall survival in children with acute leukemias." (PMID 36836180, 2023). "In acute leukemia, overexpression of MEIS1 has been consistently observed, and level of MEIS1 is inversely correlated with prognosis of this hematopoietic malignancy." (PMID 30496486, 2019). "The continued clinical evaluation of menin inhibitors may redefine treatment paradigms for NPM1m and KMT2Ar AML and other acute leukemia with the aberrant MEIS1-HOXA axis, offering new hope for patients with limited therapeutic options." (PMID 40710017, 2025). "Lastly, the clinical application of menin inhibitors is gradually expanding to include other acute leukemia subtypes characterized by MEIS1-HOXA axis activation, such as specific AML subgroups with particularly poor prognosis like NUP98-r, DEK-NUP21, and UBTF-TD." (PMID 40710017, 2025). "Thus, MEIS1 is a critical oncogenic factor in the development of acute leukemias, and its inhibition represents a promising strategy to reverse its oncogenic activity." (PMID 34698191, 2021). "Menin inhibitors are new and promising agents currently in clinical development that target the HOX/MEIS1 transcriptional program which is critical for leukemogenesis in histone-lysine N-methyltransferase 2A-rearranged (KMT2Ar) and in NPM1-mutated (NPM1mut) acute leukemias." (PMID 38651453, 2024). "Research on the disease pathomechanism in KMT2A-rearranged acute leukemias has mainly focused on the upregulation of the stemness-related genes of the HOX-family and their co-factor MEIS1." (PMID 39834944, 2024). "One of the key mechanisms of KMT2A‐r acute leukemia involves the activation of HOXA cluster genes, particularly HOXA9 and MEIS1." (PMID 39428967, 2024). "Therefore, in KMT2A‐r acute leukemia, downregulation of the HOXA and MEIS1 genes may decrease proliferation and hinder engraftment." (PMID 39428967, 2024). "In KMT2A-rearranged acute leukemia, sensitization following curaxin and panobinostat treatment is mediated by increasing histone acetylation, decreasing MYC expression, and not by altered expression of target genes HOXA9 and MEIS1." (PMID 37370721, 2023).
neuroblastoma (17 papers, 2010 to 2022). Neuroblastoma (NB) is the most common solid, extracranial childhood tumor. "The impairment of cellular proliferation, differentiated phenotype, and induced cellular death occur in the case of dominant-negative splice variants of Meis1 expression in neuroblastoma cells." (PMID 33402862, 2020). "The overexpression of Meis1 and Meis2 in neuroblastoma cells is associated with increased tumor progression." (PMID 33402862, 2020). "The inhibition of Meis1 and Meis2 expression also causes apoptosis in neuroblastoma cells." (PMID 33402862, 2020). "A dominant-negative MEIS1 splice variant was reported to yield cell clones with impaired cell proliferation, gain of differentiated phenotype, increased contact inhibition, and cell death in human neuroblastoma lines." (PMID 22163301, 2011). "Most TALE subfamilies (including Meis1, Meis2, and Pbx2) are upregulated in a set of neuroblastoma cell lines, suggesting that the regulation of TALE transcription is functional in tumorigenesis." (PMID 33402862, 2020). "In other cancers including neuroblastoma, high level expression of MEIS1 and MEIS2 genes was demonstrated, and defective MEIS1 cells showed impaired proliferation leading to cell death." (PMID 32819319, 2020). "Meis1 and Meis2 were upregulated in parallel, only in neuroblastoma, gynecologic, and thymoma cancers." (PMID 33402862, 2020). "Increased MEIS1 expression has also been observed in neuroblastomas and the expression level of the MEIS1 transcript is a prognostic indicator in breast cancer." (PMID 21858198, 2011). "However, another study showed that MEIS1 is upregulated in neuroblastoma in response to ATRA treatment." (PMID 35743243, 2022). "In particular, Meis1 was upregulated in breast, neuroblastoma, gynecologic, skin, sarcoma, and thymoma cancers, which may be associated with cancer cell survival, proliferation, and tumorigenesis." (PMID 33402862, 2020). "Deregulated MEIS1 mRNA and protein expression can lead to tumorigenesis in a number of tumor types such as acute myeloid leukemia, lung adenocarcinoma tumors, neuroblastomas, ovarian carcinomas and ESCC." (PMID 32819319, 2020). "In addition, the epigenetic inactivation of the histone methyltransferase NSD1 leads to the specifically diminished methylation of the histone lysine residues H3K36 and increases the expression of oncogene MEIS1 in human neuroblastoma and glioma." (PMID 26430963, 2015). "Hence, an increased expression of Meis1 and Meis2 may be involved in the promotion of neuroblastoma formation; thus, they may act as oncogenes." (PMID 33402862, 2020). "Thus, ATRA initiates a change in cell state of neuroblastoma cells corresponding to a shift from the adrenergic CRC to a new retino-sympathetic CRC, which includes RARA, HAND2, ISL1, TBX2, TBX3, MEIS1, and SOX4." (PMID 34669465, 2021). "Hypermethylation of Nsd1 causes the upregulation of Meis1 transcript and protein due to the absence of NSD1 binding to the Meis1 promoter in neuroblastoma cells." (PMID 33402862, 2020). "The expression levels of the control genes (MYCN, MEIS1 and ALK) were, in all three cases, when compared to all healthy samples, healthy nervous system samples and healthy peripheral nervous system samples, highly and statistically significantly elevated in neuroblastoma." (PMID 20444257, 2010).
restless legs syndrome (16 papers, 2017 to 2024). A condition that occurs while resting or lying in bed; it is characterized by an irresistible urgency to move the legs to obtain relief from a strange and uncomfortable sensation in the legs. "These analyses identified 88 candidate target-coding genes, including MEIS1, which has already been widely implicated in sleep and restless leg syndrome." (PMID 36608130, 2023). "The strongest association signal was on chromosome 2 at SNPs within gene MEIS1, known for association with Restless Leg Syndrome and Insomnia." (PMID 33075057, 2020). "MEIS1 is involved in restless leg syndrome (RLS) but recently also reported to be associated with insomnia symptoms." (PMID 31718593, 2019). "The lead SNP, rs113851554, located in a putative regulatory element in intron eight of MEIS1, is a low-frequency variant with odds ratio (OR) estimates of 1·82–2·16, which clearly distinguish it from the other risk loci for restless legs syndrome." (PMID 29029846, 2017). "The MEIS1 locus on chromosome 2 was confirmed as the strongest genetic risk factor for restless legs syndrome." (PMID 29029846, 2017). "MEIS1 was confirmed as the strongest genetic risk factor for restless legs syndrome (odds ratio 1·92, 95% CI 1·85–1·99)." (PMID 29029846, 2017). "MEIS1 encodes a developmental transcription factor and has been linked to restless legs syndrome (RLS) in genome-wide association studies." (PMID 28645892, 2017). "MEIS1 harbors the strongest risk factor for restless legs syndrome (RLS)." (PMID 39578497, 2024). "In addition, we identified a short-sleeping phenotype for the Hox cofactor, homothorax (hth), and ortholog of mammalian Meis1, which have already been implicated in sleep and human restless leg syndrome." (PMID 36608130, 2023). "Moreover, deficiency in the MEIS1 gene has been revealed to explain some of the iron or dopamine changes in relation to restless legs syndrome." (PMID 37226244, 2023). "The lead variants at these three loci are in strong to modest LD with the previously reported variants associated with restless legs syndrome (rs113851554, MEIS1, P = 2 × 10−35, LD r2 = 1.00; rs12991815, C1D, P = 2 × 10−9, LD r2 = 0.96; rs9369062, BTBD9, P = 9 × 10−14, LD r2 = 0.49)." (PMID 30952852, 2019). "MEIS1 cooperates with other transcription factors to perturb myeloid differentiation in leukemogenesis and, in genetic association studies, it has been linked with restless legs syndrome (RLS), periodic leg movements during sleep, symptoms of insomnia, PR interval and waist-to-hip ratio." (PMID 28645892, 2017). "Twenty seven SNPs were found to be associated with sleep start, including three SNPs at or near gene MEIS1 related to Restless Leg Syndrome and insomnia and nineteen SNPs at gene BTBD9 also related to Restless Leg Syndrome." (PMID 33075057, 2020). "Two of the ten new sleep duration signals, rs113851554 in MEIS1 (P = 2 × 10−25) and rs9369062 in BTBD9 (P = 2 × 10−10), have previously been associated with restless legs syndrome." (PMID 30952852, 2019). "We found that MEIS1 gene was detected as the nearest gene to the significantly associated region on CFA10, and MEIS1 was reported to be associated with restless legs syndrome." (PMID 34368281, 2021). "Although linkage results on restless legs syndrome have not been reproducible, GWASs so far have revealed six risk loci, with the strongest signal being in MEIS1, a member of the three aminoacid loop extension homeobox gene class." (PMID 29029846, 2017).
prostate carcinoma (15 papers, 2013 to 2023). A carcinoma that arises from epithelial cells of the prostate gland. "Decreased expression of MEIS1 is predicted as worse overall survival (OS) while elevated level of MEIS1 was associated with improved OS in prostate cancer." (PMID 28270206, 2017). "MEIS1 overexpression in several solid cancers has an important oncogenic function, for example, in breast, colorectal, human esophageal squamous cell, neuroblastoma, ovarian, and prostate cancers, where its upregulation has been associated to cancer etiology, progression, and increased invasiveness." (PMID 34698191, 2021). "It has been shown that MEIS1 and MEIS2 expression is associated with a more indolent phenotype of prostate cancer, with a lower risk of metastatic development." (PMID 36840946, 2023). "Deregulation of MEIS1 had been reported in cancers like prostate cancer, ovarian cancer, lung cancer." (PMID 33776902, 2021). "Knockdown of MYC expression in prostate cancer cells increased the expression of MEIS1 and increased the occupancy of MYC at the MEIS1 locus." (PMID 32681068, 2020). "Here we show that MEIS1 expression is sufficient to decrease proliferation and metastasis of prostate cancer cells in vitro and in vivo murine xenograft models." (PMID 32553107, 2020). "miRNA-204 is another key regulator in prostate cancer progression as it regulates several genes, like MEIS1 and MEIS2, as a result of protein complex dysregulation." (PMID 24391925, 2013). "In an in vitro experiment, HOXB13 and MEIS1 interact to regulate the proliferation and apoptosis of multiple prostate cancer cell lines (DU145, E006AAT, PC3, CWR22RV1, LNCaP, LNCaP C4-2, and VCap), which is believed to regulate the development of prostate cancer." (PMID 36294924, 2022). "However, it has been recently demonstrated that there is an inverse relationship between MYC activity in prostatic cancer, which drives prostate cancer progression, and MEIS1 expression." (PMID 34698191, 2021). "Meis1 and Meis2 expression determine the aggressiveness of prostate cancer." (PMID 33402862, 2020). "Meis1–3, Pbx1–3, and Hoxa9 are downregulated in lung, skin, and prostate cancers." (PMID 33402862, 2020). "A previous study reported higher expression of MEIS-1 in healthy prostate tissues than in prostate carcinoma tissues, and concluded that MEIS-1 may serve as a predictive biomarker of prostate cancer prognosis." (PMID 29632641, 2018). "High level of MEIS1 was detected in normal prostate compared with prostate tumor tissues; indicating that it would be a useful biomarker or even a therapeutic target of human prostate carcinoma." (PMID 28270206, 2017). "However, a range of recent work also revealed that MEIS1 would also be found as a negative regulator in some other cancers, e.g. non-small-cell lung cancer or prostate cancer." (PMID 28270206, 2017). "In contrast, gene expression studies in prostate cancer have shown that decreased expression of Meis1 is correlated with poor prognosis, suggesting that it may have tumor suppression activity in prostate cancer development." (PMID 25013928, 2014). "However, MEIS-1 has been reported as a negative regulator of some other cancers, such as non-small-cell lung cancer, esophageal squamous cell carcinomas, clear cell renal cell carcinomas and prostate cancer." (PMID 29632641, 2018). "Several co-regulators which have been shown to interact with other HOX proteins are expressed in the 22Rv1 prostate cancer cells, including PBX1-3, MEIS1 and MEIS3, and PKNOX1." (PMID 32012197, 2020). "Interactions between MEIS1 and HOXB13 were detectable in normal PrECs; such interactions decreased with lower MEIS expression in prostate cancer cells." (PMID 32553107, 2020). "(B) Western blot analysis of endogenous MEIS1, MEIS2, and HOXB13 expression from common prostate cancer cell lines and primary Prostate Epithelial Cell (PrEC) culture." (PMID 32553107, 2020).
prostate carcinoma (continued). "Using RNA-seq to profile a series of human prostate cancer specimens laser capture microdissected on the basis of MYC immunohistochemistry, MYC activity, and MEIS1 expression were inversely correlated." (PMID 32681068, 2020). "We thus sought to confirm a nuclear interaction between MEIS1 and HOXB13 within normal PrECs when both proteins are present and in prostate cancer cells when MEIS1 expression is increased." (PMID 32553107, 2020). "Among these works, MEIS1 is well-defined in modulating AML and prostate cancer progress." (PMID 28270206, 2017). "However, MEIS1 has also shown to be a potential tumor suppressor in some other cancers, such as non-small-cell lung cancer (NSCLC) and prostate cancer." (PMID 28270206, 2017). "Our previous work also indicated that MEIS1 functions as a negative AR regulator and inhibits the ligand-dependent growth of certain kinds of prostate cancer." (PMID 28270206, 2017). "In addition, in prostatic cancer tissues, statistically significant positive correlations between MYC and HOXB13 mRNA levels was observed, while an independent group confirmed that the tumor-suppressive activity of MEIS1 was dependent on HOXB13." (PMID 34698191, 2021). "Finally, we show in laser capture microdissected human prostate cancer samples and the prostate TCGA cohort that MEIS1 expression is inversely proportional to AR activity as well as HOXB13, a known interacting protein of both AR and MEIS1." (PMID 32681068, 2020). "Collectively, our data demonstrate that elevated MYC in a subset of primary prostate cancers functions in a negative role in regulating MEIS1 expression, and that this down-regulation may contribute to MYC-driven development and progression." (PMID 32681068, 2020).
colorectal cancer (14 papers, 2011 to 2025). A primary or metastatic malignant neoplasm that affects the colon or rectum. "The expression level of Meis1D27, a truncated splicing variant of Meis1, has been reported to be decreased in primary colorectal cancer samples." (PMID 33402862, 2020). "The ELFN1-AS1 lncRNA interacts with repressive PRC2 and DNMT3A and targets the Meis Homeobox 1 (MEIS1) promoter region in colorectal cancer cells." (PMID 40141189, 2025). "Down-regulated expression of MEIS1 was detected in colorectal cancer and predicted poor survival of colorectal cancer patients." (PMID 36836180, 2023). "The impaired expression of MEIS1 was highly correlated with the poor prognosis of colorectal cancer patients." (PMID 36836180, 2023). "To exclude the effect of tissue heterogeneity, we also determined MEIS1 methylation and expression in a panel of colorectal cancer cell lines." (PMID 24244575, 2013). "Although downregulation of MEIS1 in human colorectal cancer has recently been observed, the role of the gene in gastrointestinal (GI) homeostasis and tumorigenesis is poorly understood." (PMID 21858198, 2011). "The MEIS1 homeobox gene is known to be involved in several hematological malignancies and solid tumors and recent evidence suggests that expression of the MEIS1 transcript is altered in colorectal cancer." (PMID 21858198, 2011). "Due to the links between homeobox genes and colorectal cancer, we examined the status of Meis1 in the colon." (PMID 21858198, 2011). "MEIS1 could trigger cell proliferation in colorectal cancer, while MEIS2 determines the relationship between colorectal cancer growth and death." (PMID 33402862, 2020). "Recent evidence suggested that expression of the MEIS1 transcript was altered in colorectal cancer." (PMID 25186767, 2014). "However, MEIS1's function in colorectal cancer still needs further research." (PMID 33585439, 2020). "Several researches have shown that MEIS1 serves as a tumor suppressor in ccRCC, prostate, NSCLC, gastric, and colorectal cancers by promoting cell differentiation and inhibiting epithelial cell proliferation." (PMID 36836180, 2023). "Both the homeodomain-less isoforms of MEIS1, i.e., MEIS1D transcript and protein (27KD and 32KD), were downregulated in primary colorectal cancer samples compared to matched normal mucosa, indicating that MEIS1D was a biomarker of colorectal tumorigenesis." (PMID 25186767, 2014). "MEIS1, a potential tumor suppressor gene involved in differentiation, has a broad H3K4me3 domain in normal colon cells but not in colorectal cancer cells." (PMID 40141189, 2025). "LncRNA ELFN1-AS1 promotes DNA methylation and H3K27me3 in the promoter region of MEIS1 by guiding EZH2-DNMT3 a to locate in the promoter region of MEIS1, inhibits the transcription of MEIS1, and thus promotes oxaliplatin resistance in colorectal cancer by preventing DNA damage repair." (PMID 38970092, 2024). "Notably, three MBE motifs were discovered in the promoter region of human miR-23a, and miR-23a is highly expressed in patients with colorectal cancer (CRC), whereas MEIS1 is lowly expressed." (PMID 36834999, 2023). "Also, the epithelial colorectal cancer cell lines with MEIS1 methylation showed absence of MEIS1D27 expression." (PMID 24244575, 2013). "Genes with a broad H3K4me3 domain in normal CCD 841 CoN cells but not in colorectal cancer cells included FOXF1 adjacent non-coding developmental regulatory RNA (FENDRR) and Meis Homeobox 1 (MEIS1)." (PMID 40141189, 2025).